CD14 (CD14 molecule)
Diseases named in the same sentence as CD14 in open-access papers (continued):
Sharing a sentence is not in itself a finding about the gene and the disease.
bacterial infection (continued). "Finally, to confirm that enrichment of the neutrophil-like signature in bulk CD14+ monocytes reflects expansion of a neutrophil-like population in acute sepsis, we explored a single cell RNA-sequencing (scRNA-seq) dataset of CD14+ monocytes from patients with acute bacterial infection and sepsis." (PMID 40475424, 2025). "Therefore, during the reaction of CD14, only the sCD14 subtype, a fragment of CD14 that binds to a bacterial pathogen specific for bacterial infection and is freed from the body’s circulation, was separately detected, and a specific marker for bacterial infection was discovered." (PMID 35666350, 2022). "At the beginning of a bacterial infection, TLR4 recognize LPS and along with its co-receptor MD2 forms a complex on the surface of cells that binds to LPS facilitated by CD14." (PMID 40725160, 2025). "This study reveals that during bacterial infection, the decrease in HMGN2 levels precisely regulates the acetylation and methylation modifications of histone H3, driving a significant upregulation of CD14 gene transcription." (PMID 41246296, 2025). "The toll-like receptor (TLR) signaling pathway plays a crucial role in innate immune response activation following bacterial infection, together with the signal transduction by the pattern recognition receptor (PRR) cluster of differentiation 14 (CD14)." (PMID 39057323, 2024). "Increased CD14 and CD64 and decreased CD62L surface levels on neutrophils can be indicative of bacterial infections." (PMID 29651288, 2018). "After examination of coactivators in monocytes after bacterial infection, we found reduced expression of coactivators (i.e., CD40, CD86, MHC-II, and CD14) from TSC1 KO mice and WT mice." (PMID 27746591, 2016). "During bacterial infection, LPS extracted from the bacterial membrane is transferred to TLR4 by two accessory proteins, LPS-binding protein and CD14." (PMID 24465739, 2014). "Thus, CD44/HA and TLR4/CD14 could collaborate to diminish bacterial infection." (PMID 25354343, 2014). "In addition to its regulatory role in the expression of S100A9 and lipocalin-2 as we reported here, whether IL22 also contributes to urothelium defense mechanisms against bacterial infection by regulating HUC production of HA or HUC expression of TLR4/CD14 remains to be elucidated." (PMID 25354343, 2014). "The expression of B2m, Ctsl, Calr, and Pdia3 suggests efficient antigen processing and presentation process, and the upregulation of Rac1, and Cd14 indicats the involvement of TLR2 and TLR4, which are essential for Th1/Th17 responses elicited by wPVs or bacterial infection." (PMID 34759909, 2021). "In particular, non-classical CD14+CD16++ monocytes are expanded in bacterial infections as a potent source of cytokines." (PMID 33278000, 2021). "The simultaneously and highly enhanced expressions of TLR4 and CD14 in PBMCs of pigs co-infected with PRRSV and PCV2 might render the animal vulnerable to secondary bacterial infection observed in the field." (PMID 29157279, 2017). "Other biomarkers with one to two studies showing statistically significant differences in expression levels in bacterial infection patients compared to non-bacterial infection patients include LBP, LCN-2, lactoferrin, sPLA2, D-Lactate in CSF, EDA-FN, FN, and soluble CD14." (PMID 27486746, 2016). "In case of chronic inflammation and bacterial infections, the cell wall component of Gram-negative bacteria LPS is bound to CD14 membrane protein necessary for activation of MC via Toll-like receptor 4 (TLR4) which initiates cytokine and chemokine production in MC." (PMID 35163137, 2022). "The anti-inflammatory effects of vitamin D during bacterial infection were demonstrated, such as the decreased cytokine production in ex vivo PBMC and monocytes treated with bacterial ligands and calcitriol, as was the protection against bacterial infection due to the increase of CD14 expression." (PMID 35408981, 2022).
bacterial infection (continued). "A soluble, truncated protein fragment of the macrophage surface protein CD14, PSP is a hypothetically appealing CNS infection marker as it is produced in the systemic circulation by macrophages, and thus likely secreted by CNS microglia, in response to bacterial infection." (PMID 29497398, 2018). "Our observational studies in humans imply that the numbers of intermediate (CD14++CD16-) monocytes, which we have previously shown express higher levels of CCR2 with age, correlate with increased levels of TNF and contribute to hyper-inflammatory responses to bacterial infection." (PMID 26766566, 2016). "In addition to the recognition and internalization of LPS, the differentiation of monocytes to macrophages is accompanied by regulation of CD14 and data suggest that CD14 is essential for TNF-α production, this being the most proinflammatory cytokine produced during bacterial infection." (PMID 26793196, 2015). "Soluble CD14 bound to LPS and LBP can then bind to endothelial and epithelial cells to activate cytokine secretion thereby allowing nonmyeloid cells a way to respond to bacterial infections." (PMID 36290196, 2022). "Since cytokines released by monocytes pivotally determine survival during bacterial infections, we analysed induction of IL-6, IL-1beta and TNF-alpha separately in TLR-stimulated classical CD14++CD16−, intermediate CD14++CD16+ and non-classical CD14+CD16++ monocytes." (PMID 33278000, 2021). "During bacterial infection, 24-OHase expression was not significantly higher in CD14+ cells from the infected glands compared to the CD14+ cells from blood, but was higher in CD14− cells from the infected glands compared to CD14− cells from blood (P<0.05)." (PMID 21124742, 2010).
cardiovascular disease (39 papers, 2012 to 2025). "They identified apolipoprotein B, CD14, and pro-basic platelet protein as proteomic markers associated with an increased incidence of cardiovascular disease in women compared to men." (PMID 39336514, 2024). "The activated monocyte population (typically CD14++ classical monocytes) is associated with cardiovascular disease in adults, and with increased gene expression for monocyte activation in children that have elevated markers of cardiovascular disease." (PMID 32528415, 2020). "We conducted a meta-analysis to evaluate the effects of CD14 polymorphisms (rs2569190 and C-159T) on the risk of cardiovascular disease." (PMID 30922395, 2019). "In previous studies on the LPS-related factors, sex-adjusted association was observed between LBP/soluble CD14 and aortic stiffness, carotid intima-media thickness, and cardiovascular disease." (PMID 28486964, 2017). "To date, there are limited data regarding the probability of cardiovascular diseases according to CD14 genetic polymorphisms in Korean population." (PMID 24228026, 2013). "Thus, high numbers of proinflammatory CD14++CD16+ monocytes were associated with the risk of cardiovascular disease and death in a cohort of 94 dialysis patients." (PMID 33353159, 2020). "Furthermore, other investigators demonstrated an association between cardiovascular disease and increased CD14+ MVs and total MV concentration." (PMID 30425991, 2018). "With the work on monocyte subsets in cardiovascular disease in mind, the intermediate CD14++CD16+ monocytes can doubtless be seen as a subset with a proinflammatory functions." (PMID 27991581, 2016). "This highlights the importance of CD14++ monocytes in cardiovascular diseases." (PMID 34796212, 2021). "We believe that blockade of CD14 on the cell surface and clinical use of anti-CD14 mAbs or their Fab fragments may diminish ROS production and improve outcomes during cardiovascular diseases manifested by LPS-induced inflammation." (PMID 30944694, 2019). "We believe that blockade of CD14 on the cell surface and clinical use of anti-CD14 mAbs or their Fab fragments may diminish the production of ROS and improve outcomes during cardiovascular diseases manifested by LPS-induced inflammation." (PMID 30944694, 2019). "Moreover, the relatively low abundance of urinary CD14 in subjects with normal coronary conditions may suggest the diagnostic and prognostic potentials to apply this CD14 as a sensitive biomarker for the detection of early cardiovascular disorders in selected cohort of populations." (PMID 25668619, 2015). "More recently, the importance of CD14++CD16+ monocytes in cardiovascular disease was reinforced by the finding from Heine’s group that CD14++CD16+ monocytes could independently predict cardiovascular events in a large cohort." (PMID 23593194, 2013). "Indeed, most studies that have found an association between hsCRP and the CD14 C-260T SNP have so far been in populations that have already developed cardiovascular disease and unlike our study participants who had subclinical disease." (PMID 25622527, 2015). "The CD14+/CD16+ “proinflammatory” monocyte subpopulation is preferentially susceptible to HIV infection and may play a critical role in the pathogenesis of HIV-related cardiovascular disease." (PMID 22645407, 2012). "In human cardiovascular diseases (CVD) and inflammatory conditions, the inflammatory intermediate CD14+CD16+ monocyte is increased, and they have been shown to interact with T cells, influencing immune activation and antigen presentation." (PMID 40430089, 2025). "Although patients with concurrent cardiovascular disease had higher percentages of CD8+ TEMRA cells and CD14++CD16+ intermediate monocytes in their peripheral blood, the differences between groups were relatively small regarding a given immune subset." (PMID 30455721, 2018).
cardiovascular disease (continued). "Non-insulin-dependent diabetic subjects with cardiovascular disease depicted increased CD14 levels on the surface of CD14++/CD16- monocytes." (PMID 34064071, 2021). "Patients with previous cardiovascular disease had higher numbers of CD14+/endoglin+ cells than those without previous cardiovascular disease." (PMID 29304136, 2018). "The non-classic monocyte subset (CD14+CD16++) produces pro-inflammatory cytokines and plays a role in cardiovascular disease." (PMID 25485543, 2014). "Verification of the migration assay in BM cells from subjects without a cardiovascular disease background confirms the depletion of CD3+ lymphocytes and CD34+ and CD133+ PCs along with enrichment of CD14++CD16−, CD14++CD16+ and CD14+CD16++ monocytes in the SDF-1-attracted fraction." (PMID 25889213, 2015). "This study investigated whether circulating levels of GDF‐15, E‐selectin, CD14, and ST2 are predictors of death and cardiovascular outcomes in 981 individuals who did not have a history of cardiovascular disease (CVD) during follow‐up periods of 5, 10, and 20 years." (PMID 40495286, 2025).
infectious disease (14 papers, 2011 to 2024). A disorder directly resulting from the presence and activity of a microbial, viral, or parasitic agent in humans. "Some of these had been previously associated to a worse prognosis in HIV and other infectious diseases, or related to inflammatory status (IL-6, CD14, CD163, IRAK-M, and TNFα)." (PMID 34211989, 2021). "Upregulated DEGs detected in CD14+ cells at day 3 were involved in virus sensing (infectious disease: RNA virus and infectious disease: viral), PRR signaling (NOD-like receptor signaling), and chemokine signaling." (PMID 37920474, 2023). "Although the function of soluble salivary CD14 in human disease has not yet been clear, a potential pathogenic role of soluble CD14 in several infectious diseases has been proposed." (PMID 28936284, 2017). "In studies in infectious diseases (HIV, HCV), gMDSC were defined to lack the expression of CD14 but to express CD15/CD33/CD11b whereas mMDSC were characterized as CD14+/CD11b+/HLA-DR−/low cells or additionally CD33+ cells." (PMID 26733325, 2016).
inflammation (14 papers, 2010 to 2025). Aberrant reaction of the microcirculation characterized by movement of fluid and leukocytes from the blood into extravascular tissues. "TLR4 activation leads to increased expression of inflammatory genes such as NF-κB, Myd88, and CD14, resulting in the production of inflammatory cytokines (IL-1β, IL-6, TNF-α), which cause liver inflammation and damage." (PMID 40362886, 2025). "The increased CD14+ monocytes in peripheral blood provided OCPs and contributed to active osteoclastogenesis and joint inflammation in PsA." (PMID 38672131, 2024). "In both a mouse model of HBV-induced liver inflammation and patients with advanced viral-related chronic liver disease, the intrahepatic CD14+HLA-DRhighCD206+ myeloid population is proinflammatory and spontaneously produces high levels of TNF-α." (PMID 38413535, 2024). "Overall, these results demonstrate that CD14 is an inflammatory receptor that contributes to lung inflammation and mortality induced by TsV via PGE2–cAMP–IL-1β release." (PMID 29755470, 2018). "Further studies are required to disentangle the dual role of CD14 in LPS-induced acute lung inflammation." (PMID 20419140, 2010). "The aim of the present study was to investigate the role of CD14 in the induction of acute lung inflammation by these different LPS chemotypes." (PMID 20419140, 2010). "Acute lung inflammation induced by low doses S-LPS or R-LPS was dependent on CD14, whereas inflammatory responses induced by high LPS doses were diminished in the presence of CD14." (PMID 20419140, 2010). "There is a body of evidence supporting GM-CSF as an important mediator in lung inflammation by upregulating TLR2, TLR4, and CD14 expression, and by boosting IL-6 and IL-1β production from macrophages." (PMID 30013577, 2018).
metabolic disorders (13 papers, 2012 to 2024). "CD14 is a pattern recognition receptor that has been implicated in inflammation, the innate immune response, metabolic disorders, and tumorigenesis and can hyperactivate microglia." (PMID 39767701, 2024). "Further, CD14 has been suggested to play additional roles in metabolic diseases besides inflammation." (PMID 38817635, 2024). "Studies have identified that CD14 plays a critical role in inflammatory diseases, metabolic diseases, tumors, and other diseases." (PMID 34233597, 2021). "CD14, a cell-surface molecule involved in innate immunity, is a systemic modulator of LPS-induced metabolic disorders." (PMID 23133617, 2012). "The minor CD16+ Mo subpopulation comprises the remaining 10–15% and is subdivided further into intermediate monocytes (IM; CD14+CD16+) and non-classical monocytes (NCM; CD14-CD16++), both with a pro-inflammatory phenotype and are elevated in chronic inflammatory and metabolic diseases." (PMID 32074122, 2020).
neurodegenerative disease (13 papers, 2004 to 2025). A disorder of the central nervous system characterized by gradual and progressive loss of neural tissue and neurologic function. "eQTL analysis of six neurodegenerative disease variants in CD14+ monocytes." (PMID 30619483, 2018). "Relevant to a broader range of neurodegenerative diseases, novel peptides and neoantigens exposed by apoptotic cells also activate CD14-dependent innate immune response in macrophages." (PMID 15498098, 2004). "The answers could help develop TREM2- and CD14-targeted therapy to treat AD and related neurodegenerative diseases." (PMID 37483607, 2023). "We used a model of selective activation of CD14/TLR4 co-receptors that is now appreciated to initiate innate immune response to endogenous ligands relevant to neurodegenerative diseases such as Aβ fibrils as well as peptides and neoantigens expressed by apoptotic cells." (PMID 16603079, 2006). "CD14 + MALAT1 + monocyte DEGs were enriched in mitochondrial ATP synthesis-coupled electron transport and some neurodegenerative disease-related pathways." (PMID 37041166, 2023). "Of interest, the CXCR7 inhibitor CCX771 was recently described to interfere with CXCL12-directed migration of CXCR7-positive CD14+ CD16+ monocytes of HIV-infected people into the CNS, which can result in a neurodegenerative disease termed NeuroAIDS." (PMID 29560468, 2018). "We next used quantitative immunoblotting to verify the MS data for a subset of candidate biomarkers, with a focus on proteins known to have a role in neuron biology, neuroinflammation, neurodegenerative diseases, and/or pathophysiology in general: NP1, Ch3L1, CD14, and IGFBP2." (PMID 34054689, 2021). "Indeed, screening of innate immune receptors in animal models of AD, PD/DLB, and ALS revealed upregulation of TLR2 and CD14 as a common feature in all neurodegenerative diseases and therefore likely part of a non-specific effector phase common to many neurodegenerative diseases." (PMID 35979366, 2022).
immune dysfunction (12 papers, 2016 to 2026). "Functional analysis revealed impaired antigen processing and presentation in CD14+ monocytes, and dysregulated transcription factor activity, potentially driving immune dysfunction." (PMID 41273773, 2026). "In the long term, our findings point to studies on the regulatory mechanisms in mPs and CD14+ monocytes as a fruitful area for further research on the mechanisms leading to immune dysfunction after severe injury." (PMID 33320841, 2021). "These miRNAs are closely related to the expression of CD3, CD14, CD19, and CD56 in four immune cells, indicating that both MDD and GBM can cause immune system disorders." (PMID 29329273, 2018). "In that sense, PD-L1 expression in CD14+ monocytes not only may play a role in immune dysfunction but also may be an early indicator of IC in AP." (PMID 28705256, 2017). "In addition, it has recently been demonstrated that mortality in HIV and M. tuberculosis co-infected patients is linked to immune dysfunction of monocytes, especially related to inflammatory mediator production of IL-6, TNFα, and CSF3 and expansion of CD16+CD14+ monocytes." (PMID 29770360, 2018). "HZOL can reverse LPS-induced changes relating to the inflammatory cytokines and immune dysfunction and attenuating the expressions of TLR4, CD14, MyD88, NF-κB p65, and p-NF-κB p65 of the TLR4/NF-κB p65 pathway." (PMID 36845637, 2023). "We found decreased circulating lymphocyte counts and HLA-DR expression in CD14+ monocytes in patients with IC compared with those without IC, which is consistent with the phenomenon of immune dysfunction." (PMID 28705256, 2017).